MCM7 (minichromosome maintenance complex component 7)
Diseases named in the same sentence as MCM7 in open-access papers (continued):
Sharing a sentence is not in itself a finding about the gene and the disease.
gastric cancer (11 papers, 2011 to 2023). A primary or metastatic malignant neoplasm involving the stomach. "The 7q21-22 amplification, MCM7, and its intronic miR-25 have also been conclusively demonstrated to represent the three primary molecular switches in the complex oncogenic circuits of gastric cancer." (PMID 37594635, 2023). "Moreover, we proved that the increased expression of MCM7 in early gastric cancer was consistent with the expression of Ki67, reflecting the proliferation status of the evaluated cells." (PMID 36061145, 2022). "Knockdown of MCM7 can inhibit the proliferation of gastric cancer cells." (PMID 34993142, 2021). "The up-regulated level of MCM7 is a useful biomarker in the early diagnosis of gastric cancer." (PMID 34993142, 2021). "Moreover, MCM7 is also a promising biomarker for early diagnosis of gastric cancer and even a predictor of meningioma recurrence after surgery." (PMID 33564675, 2021). "The combination of MCM7 and Ki67 may serve as more sensitive proliferation markers for the evaluation of gastric carcinoma." (PMID 32596300, 2020). "In addition, MCM7 has been helpful in early detection of gastric cancer (GC), and altered diagnosis between malignant mesothelioma (MMCS) and reactive mesothelial cells (MCS)." (PMID 31323040, 2019). "Interestingly, another study using human gastric cell lines also reported that the amplification of MCM7 and its intron miR-25 might be the major molecular switchers in the development of gastric cancer." (PMID 29765562, 2018). "In summary, we first demonstrated that NOL6 can regulate the oncogenic behaviors of gastric cancer cells by down-regulating TP53I3 and up-regulating CDK4, MCM7." (PMID 35494047, 2022). "In gastric cancer cells, E2F1 also appears to regulate miR-106b-25 expression in parallel with increases in MCM7 expression." (PMID 21283757, 2011). "E2F1 may be crucial in the development of gastric cancer by influencing the cell cycle pathway and modulating its target gene MCM3, which may interact with MCM4, MCM5, and MCM7." (PMID 37594635, 2023).
non-small cell lung carcinoma (11 papers, 2011 to 2025). A group of at least three distinct histological types of lung cancer, including non-small cell squamous cell carcinoma, adenocarcinoma, and large cell carcinoma. "In this study, we investigated the role of lamin B2 and its association with MCM7 in non-small cell lung cancer (NSCLC)." (PMID 29285216, 2017). "LMNB2, a B type nuclear lamin, binds to the C-terminus of MCM7 and competes with the binding of the tumor suppressor RB protein, thus regulates human non-small-cell lung cancer progression." (PMID 33102573, 2020). "In this report, we demonstrate that RACK1 regulates cell growth and cell cycle progression in human non-small-cell lung cancer by mediating MCM7 phosphorylation through an MCM7/RACK1/Akt signaling complex." (PMID 28465488, 2017). "Immunohistochemical analysis showed that MCM7 was positively stained in 196 of 331 non-small cell lung cancer (NSCLC), 21 of 29 bladder tumor and 25 of 70 liver tumor cases whereas no significant staining was observed in various normal tissues." (PMID 21619671, 2011). "Furthermore, non-small cell lung cancer (NSCLC) patients with lower MCM-7 expression tended to have concomitant bronchioloalveolar carcinomas compared with those with higher MCM-7 expression." (PMID 34272446, 2021). "Moreover, MCM7 participated in regulating cell growth and cell cycle progression in non-small-cell lung cancer through a MCM7/RACK1/Akt signaling complex." (PMID 33505310, 2020). "Additionally, YAP activates the transcription of MCM7 in non-small cell lung cancer." (PMID 40789837, 2025). "MCM7 expression is known to be regulated by various intracellular signaling pathways, including the YAP/TAZ pathway in non-small cell lung cancer." (PMID 40789837, 2025). "In non-small-cell lung cancer (NSCLC), downregulation of MTHFD2 expression suppresses the expression of cell cycle-related genes, such as CCNA2, MCM7, and SKP2." (PMID 35693982, 2022).
cervical carcinoma (10 papers, 2005 to 2025). A carcinoma arising from either the exocervical squamous epithelium or the endocervical glandular epithelium. "In particular MCM7 constitutes a reliable human cervical cancer marker." (PMID 31640696, 2019). "Interestingly, levels of members of the Minichromosome Maintenance (MCM) family (MCM2, MCM3, MCM4, MCM5, MCM6, MCM7) were found to be highly significantly increased in cervical cancer tissue from early and late stage patients as compared to healthy tissue." (PMID 29719595, 2018). "Expression of MCM7, cervical cancer biomarker, was similar in all cancers." (PMID 27911853, 2017). "MCM7 was also proposed as an informative biomarker in cervical cancer." (PMID 18349847, 2008). "The MCM7 gene could play an important role in cervical cancer cells, allowing cellular replication." (PMID 40361484, 2025). "In cervical cancer, bladder cancer, cutaneous melanoma, and oral squamous cell carcinoma, MCM4 and MCM7 have been reported to be promising prognostic markers for disease progression." (PMID 27476776, 2016).
colorectal cancer (10 papers, 2010 to 2024). A primary or metastatic malignant neoplasm that affects the colon or rectum. "Next, we investigated the impact of MCM7 knockdown in other colorectal cancer cell lines harboring KRAS or BRAF mutations." (PMID 32612138, 2020). "Here we demonstrate that the suppression of MCM7 is synthetic lethal in KRAS mutated colorectal cancer cells, which specifically rely on high MCM7 levels." (PMID 32612138, 2020). "MCMs expression was significantly up-regulated in variety of tumors and the expression of MCM7 has been reported as an independent risk factor for relapse-free survival and correlated with poor outcome in patients with colorectal cancer, oesophageal squamous cell carcinoma and glioma." (PMID 25823655, 2015). "MCM7 was identified as a direct target of PRMT5 in colorectal cancer, and both MCM7 and PRMT5 were up-regulated in CRC tissue and promoted cell proliferation, migration and invasion." (PMID 34859821, 2021). "In conclusion, we provide evidence that oncogenic KRAS expression sensitizes colorectal cancer cells to inhibition of DNA replication origin licensing by suppression of the replication factor MCM7." (PMID 32612138, 2020). "In the gastrointestinal tract, MCM7 expression was found to be a poor prognostic factor for gastric and colorectal cancer." (PMID 27476776, 2016). "For example, MCM7 (minichromosome maintenance protein 7) is the host gene for three of the miRNAs (miR-25, miR-93 and miR-106b) we identified and has been reported to be amplified or over-expressed in human malignancies including prostatic, pancreatic, thyroid, cervical and colorectal cancers." (PMID 20838434, 2010). "In pancreatic and colorectal cancers, PAK2 interacts closely with the tumor microenvironment and cellular modulators like Mps one binder 1 (MOB1) and minichromosome maintenance complex component 7 (MCM7), emphasizing the need for context-specific therapeutic strategies." (PMID 39769207, 2024).
liver cancer (10 papers, 2011 to 2025). An epithelial or non-epithelial malignant neoplasm that arises from the liver. "MCM7 enhances stemness via autophagy in bladder cancer and is associated with cisplatin resistance in both bladder cancer and liver cancer via PI3K/AKT signaling." (PMID 41375045, 2025). "According to previous study, MCM7 has also been reported as a promising target for different cancer types, such as liver cancer, acute myeloid leukemia and COAD." (PMID 35693940, 2022). "Arsenic trioxide has been shown to suppress liver cancer cells metastasis by targeting the SRF/MCM7 complex." (PMID 34277436, 2021). "The researchers additionally reported that ATO can inhibit stem cell proliferation and metabolism of liver cancer cells by targeting the SRF/MCM7 complex." (PMID 34413873, 2021). "In the MCM family, abnormal expression of MCM2, MCM3, MCM4, MCM5, and MCM7 also results in reducing prognosis in liver cancer patients according to the HCCDB database." (PMID 32082966, 2019). "MCM7 promotes liver cancer progression through cyclin D1-dependent signaling." (PMID 33952716, 2021). "In our microarray expression analysis, we confirmed elevated MCM7 expression in various types of cancers including lung, bladder and liver, and tissue microarray immunohistochemical analysis showed up-regulation of MCM7 in liver cancer tissues at the protein level (25/70, 35.7%)." (PMID 21619671, 2011).
glioma (8 papers, 2014 to 2025). A benign or malignant brain and spinal cord tumor that arises from glial cells (astrocytes, oligodendrocytes, ependymal cells). "In previous studies, it has been widely verified that high expression of MCM7 or CDK6 is closely related to the malignant proliferation of glioma cells." (PMID 37005685, 2023). "Univariate and multivariate analyses revealed that MCM2, MCM4, MCM6, MCM7 expression and tumor grade, 1p/19q codeletion, primary therapy outcome, and age were independent factors correlated with poor clinical outcomes of glioma patients." (PMID 36465369, 2022). "Univariate and multivariate analyses revealed that MCM2, MCM4, MCM6, MCM7 expression and tumor grade, 1p/19q codeletion, primary therapy outcome, and age were independent factors that influenced the clinical outcome for glioma patients." (PMID 36465369, 2022). "Univariate and multivariate analyses uncovered that MCM2, MCM4, MCM6, MCM7 expression, tumor grade, and age were independent factors that influence the clinical outcome of glioma patients." (PMID 36465369, 2022). "In conclusion, the results suggest that MCM2, MCM3 and MCM7 play important roles in glioma tumor progression." (PMID 25046975, 2014). "Compared with previous reports, we confirmed MCM 2, MCM 3 and MCM7 expression were correlated with WHO grading of glioma tumors on mRNA profiles by microarray data analysis and qPCR." (PMID 25046975, 2014). "Most notably, MCM2, MCM3 and MCM7 aberrations in glioma tumors portend a particularly aggressive clinical behavior." (PMID 25046975, 2014). "To confirm the specificity of the qPCR results, we characterized MCM2, MCM3, MCM7, as well as β-actin as a loading control, in six glioma samples for which freshly frozen materials were available." (PMID 25046975, 2014). "MCM2, MCM3 and MCM7 proteins expression is also known to be an important tool for estimating tumor proliferation and a useful adjunct to the routinely used proliferation markers for glioma diagnosis." (PMID 25046975, 2014). "High expression of MCM 2, MCM3 and MCM7 mRNA correlated with poor outcome and may be clinically useful molecular prognostic markers in glioma." (PMID 25046975, 2014). "Thus the expression level of MCM2, MCM3 and MCM7 reveal information on the survival probability for patients with glioma beyond that revealed by grade alone." (PMID 25046975, 2014). "Interestingly, we found that there are several putative binding sites of NF-κB p50 and p65 on the promoter of MCM7, which suggesting that NF-κB might be involved in the upregulation of miR-93 in glioma." (PMID 25823655, 2015). "In this research, we uncovered that copy number variations of MCM7, MCM9 and MCM3 were significantly positively correlated with its expression in glioma." (PMID 36465369, 2022). "CNV analysis results confirmed that copy number variations of MCM7, MCM9, and MCM3 were significantly positively correlated with its expression in glioma." (PMID 36465369, 2022). "An immunoreactive band of MCM2, MCM3 and MCM7 were seen in all six cases of gliomas, MCM2, MCM3 and MCM7 expressions were significantly higher in malignant tissues than in tissues with low malignant potential." (PMID 25046975, 2014).
lung adenocarcinoma (8 papers, 2014 to 2023). A carcinoma that arises from the lung and is characterized by the presence of malignant glandular epithelial cells. "MCM7 is up-regulated in lung adenocarcinoma and is associated with poor prognosis." (PMID 34993142, 2021). "Studies also showed MCM7 expression had poorer prognosis in lung adenocarcinoma." (PMID 27476776, 2016). "Immunohistochemistry (IHC) demonstrated that mRNAs DLGAP5, MCM7, RACGAP1, and RRM2 were upregulated in lung adenocarcinoma (LUAD)." (PMID 32149133, 2020). "In addition, the high expression levels of H2AFX, MCM2, MCM7, and POLD1 correlate with poor prognosis of lung adenocarcinoma (LUAD)." (PMID 33442399, 2021).
esophageal cancer (7 papers, 2015 to 2023). A primary or metastatic malignant neoplasm involving the esophagus. "Examined were the roles and mechanisms of MCM7 amplification and overexpression in the development of oesophageal cancer." (PMID 37594635, 2023). "In esophageal carcinoma cell lines, high MCM7 expression induced cell proliferation, colony formation and migration by regulating the AKT1/mTOR messenger system." (PMID 34144903, 2022). "The diagnostic values of the individual MCM subunits were identified in various cancers including MCM2 in gastric cardiac cancer and salivary gland tumor, MCM5 in esophageal cancer, MCM7 in meningiomas, and MCM10 in breast cancer." (PMID 32089988, 2020). "In pairwise mean comparisons, the percentages of MCM4 and MCM7 expression was significantly greater than the percentages of Ki-67 expression in esophageal carcinoma and most of the precancerous lesions." (PMID 27476776, 2016). "In summary, our findings demonstrated the percentages of MCM4 and MCM7 expression significantly correlated with Ki-67, Bmi1, and cyclin E expression in esophageal carcinoma and precancerous lesions." (PMID 27476776, 2016). "We also demonstrated the percentage of MCM4 and MCM7 expression to be significantly correlated with Ki-67, Bmi1, and cyclin E expression in esophageal carcinoma and precancerous lesions." (PMID 27476776, 2016). "MCM4 and MCM7 expression had similar distribution as Ki-67 and Bmi1 expression in esophageal carcinoma and pre-cancerous lesions." (PMID 27476776, 2016). "Values close to mean percentages of MCM4 (70%), MCM7 (70%) and Ki-67 (25%) expression had the best association between MCM4, MCM7 and Ki-67 expression and overall survival in esophageal carcinoma." (PMID 27476776, 2016). "The literature on MCM4 and MCM7 expression in esophageal cancer is limited." (PMID 27476776, 2016). "MCM4 and MCM7 may serve as more sensitive proliferation markers for evaluation of esophageal carcinoma and precancerous lesions." (PMID 27476776, 2016). "In this study, we investigated CA9 expression in esophageal cancers and in precancerous lesions and explored the association of CA9 expression with prognostic factors and with stem cell and tumorigenesis-related markers including BMI1, cyclin E, ki67, MCM4 and MCM7 expression." (PMID 26156831, 2015). "Silencing of MCM7 inhibited the phosphorylation of AKT1 and mTOR in both esophageal cancer cell lines, suggesting that MCM7 might promote cancer development and poor survival outcomes via activating the AKT1/mTOR signaling pathway." (PMID 32089988, 2020). "While limited studies on MCM4 and MCM7 expression in esophageal carcinoma have been reported, none of the studies to the best of our knowledge investigated MCM4 and MCM7 expression by immunohistochemistry." (PMID 27476776, 2016).
melanoma (7 papers, 2020 to 2023). A malignant, usually aggressive tumor composed of atypical, neoplastic melanocytes. "The early stage of regeneration (1dpa) and melanoma is characterized by the upregulation of genes, including cdk2, mcm7, pcna, mki67, and cdk1, associated with proliferation and cell cycle." (PMID 38020918, 2023). "MCM7 was involved in oncogenic signaling pathways and was highly expressed in various tumor tissues, including melanoma." (PMID 34490114, 2021). "MCM7 silencing promoted autophagy and apoptosis, which inhibited the migration, viability, and invasion of tumor cells in melanoma." (PMID 34490114, 2021). "On the other hand, proliferation-related genes, including cdk2, minichromosome maintenance complex component 7 (mcm7), pcna, marker of proliferation Ki-67 (mki67), and cdk1 were upregulated in the melanoma tissues while being unaltered in nevi, when compared to the control." (PMID 38020918, 2023). "Male-specific DEGs include MCM7, a DNA replication licensing factor; NKX2-2, an important biomarker for metastatic prostate cancers; and NGFR, the canonical single-pass transmembrane receptor linked to melanoma and squamous cell carcinoma." (PMID 35158998, 2022). "Interestingly, we found that MCM7 was significantly downregulated in MCM2-knockdown groups, indicating the MCM7 may be essential link for MCM2 promoting melanoma cell proliferation." (PMID 35693940, 2022). "Except for MCM7, MCM1–6 and MCM8–10 were all highly expressed in metastatic melanoma than in primary melanoma in the TCGA cohort (P < 0.05)." (PMID 34490114, 2021). "Moreover, a link between MCM7 and the PI3K pathway has previously been reported for human melanoma and esophagal squamous carcinoma, and an inhibitory role of the MCM7 locus on the PI3K antagonist PTEN was observed in a transgenic mouse model." (PMID 35192608, 2022). "We additionally confirmed the expression with mRNA levels of key genes after treatment with lj-1-59 in melanoma cells, which indicated that P21, BBC3, SESN2 and GADD45A expression were significantly upregulated, while MCM2, MCM3, MCM4, MCM7 and PKMYT1 were significantly downregulated." (PMID 32021565, 2020). "In our study, although it was not statistically significant, we found that MCM7 was more highly expressed in melanoma than in normal skin, and increased expression of MCM7 was correlated with worse outcomes in melanoma, which is consistent with its oncogenic role." (PMID 34490114, 2021).